IFNGR1 (interferon gamma receptor 1)
Diseases named in the same sentence as IFNGR1 in open-access papers (continued):
Sharing a sentence is not in itself a finding about the gene and the disease.
colorectal cancer (13 papers, 2016 to 2025). A primary or metastatic malignant neoplasm that affects the colon or rectum. "In colorectal cancer, palmitoylation-driven lysosomal degradation of Interferon gamma receptor 1 (IFNGR1), upon optineurin depletion, impairs the IFNγ and MHC-I pathways, leading to immune evasion and intrinsic resistance to immunotherapy." (PMID 38067206, 2023). "For example, in colorectal cancer cells, stability of IFNGR1 was found to be negatively regulated by palmitoylation; although, the specific ZDHHC that palmitoylates IFNGR1 was not identified." (PMID 37759431, 2023). "We next compared the expression levels of IFNGR1 in 65 pairs of human colorectal cancers and normal mucosa tissues (GSE20842))." (PMID 27286456, 2016). "Additionally, OPTN plays a critical role in preventing immune evasion in colorectal cancer by maintaining interferon-gamma receptor 1 (IFNGR1) expression and supporting dendritic cell-mediated T-cell priming, thereby enhancing antitumor immune responses." (PMID 41294799, 2025). "Consequently, pharmacological targeting of IFNGR1 palmitoylation stabilizes IFNGR1, augments T-cell immunity, and increases sensitivity to checkpoint treatment in colorectal cancer." (PMID 40066091, 2025). "Thus, loss of optineurin impairs the integrity of the IFNγ- and MHC-I-signaling pathways via IFNGR1 degradation, thereby driving immune evasion and intrinsic immunotherapy resistance in colorectal cancer." (PMID 34385592, 2022). "The anticancer activity of IFNs which involving its receptors was clearly shown by the study of the administration of IFN-γ which led to the inhibition of colorectal cancer cell proliferation, while the knockdown of IFNGR1 stimulated cell proliferation and colony formation potential." (PMID 32636590, 2020). "Interestingly, the upregulated genes in tumors of Ifngr1−/−ApcMin/+ mice were found to be more likely to overlap with those upregulated in human colorectal cancers (p-value = 0.0018)." (PMID 27286456, 2016). "Since IFNGR1 expression was downregulated in human colorectal cancers, we next interrogated whether the expression levels of IFNGR1 were correlated with prognosis of cancer patients using the public available databases GSE14333 and GSE17536." (PMID 27286456, 2016). "Thus, IFNGR1 palmitoylation promotes IFNGR1 degradation and instability in colorectal cancer cells." (PMID 34385592, 2022). "IFNGR1 in colorectal cancer cells can be palmitoylated, which allows its interaction with AP3D1, a lysosome sorting adapter, and facilitates IFNGR1 lysosomal sorting and degradation." (PMID 34385592, 2022). "Targeting IFNGR1 stability, including palmitoylation, may be a promising approach to overcome intrinsic ICB resistance in patients with colorectal cancer." (PMID 34385592, 2022). "Given that IFNGR1 palmitoylation is essential for its interaction with AP3D1 and subsequent IFNGR1 lysosomal sorting and degradation in colon cancer, suppression of IFNGR1 palmitoylation can restore cancer IFNγ signaling integrity and sensitize colorectal cancer cells to immunotherapy." (PMID 34385592, 2022).
COVID-19 (13 papers, 2021 to 2025). A disease caused by infection with severe acute respiratory syndrome coronavirus 2. "The increase of IFNγ indicates a Th1-skewed response during COVID-19, and the increase in mRNA IFNγR1 transcription factor further supported this." (PMID 37569646, 2023). "We also found that the elevated pro-inflammatory cytokines (IFNGR1, IFNGR2, and TGFB2) were significantly co-expressed with ACE2 in male squamous cells from critically ill COVID-19 patients." (PMID 34330889, 2021). "IFNGR1, the receptor for IFNG, was significantly reduced in the obese patients with COVID-19." (PMID 37361874, 2023). "The hypermethylated genes with the lowest p values for hospitalized COVID-19 patients at inclusion (T1) vs. at 6 weeks post-inclusion (T2) were PARP9, ABCA1, MX1, OAS1, ARID5B, and the hypomethylated genes included TMEM131, ROCK1, IFNGR1, CFAP61, VRK2, and C6orf138." (PMID 41227320, 2025). "In agreement with our finding that adult Ifngr1−/− mice phenocopied the disease course of aged WT animals, we found that treatment of aged mice with IFN-γ prevented severe disease progression, supporting the view that IFN-γ limits age-dependent COVID-19 severity." (PMID 36129445, 2022).
tuberculosis (13 papers, 2012 to 2023). A chronic, recurrent infection caused by the bacterium Mycobacterium tuberculosis. "One patient was diagnosed with tuberculosis, one with atypical mycobacterial infection caused by an inborn IFNGR1 mutation, two with rheumatological disorders, and two with other infectious diseases." (PMID 36831520, 2023). "Interferon-gamma (IFNG) and its receptor (IFNGR1) are principal genes that associated with tuberculosis." (PMID 29228700, 2017). "In contrast, the functional investigation of the SNP at the AP-4 binding site at position −56 (T to C) in the promoter of interferon-gamma receptor 1 (IFNγR1) gene in tuberculosis patients and other ethnic groups, showed loss of promoter activity." (PMID 22509293, 2012). "Since all these words have a higher chance of probability to be mentioned within a sentence and especially IFNGR1 (cosine distance-0.468307) is a gene and various study have been conducted to reveal the association between its polymorphisms and risk of tuberculosis." (PMID 30048465, 2018). "Several studies have demonstrated that susceptibility to tuberculosis may be associated with IFNGR1 gene polymorphisms." (PMID 29209098, 2017). "Several studies have shown that susceptibility to tuberculosis may be associated with IFNGR1 gene polymorphisms." (PMID 29209098, 2017). "The association of IFN-γ receptor 1 (IFNGR1) gene polymorphisms with tuberculosis (TB) susceptibility has not been systematically studied." (PMID 36148347, 2022). "Over the years, several studies have identified genetic polymorphisms associated with different molecules in the IFN-γ induction pathway, especially T-Bet, STAT1, and IFNGR1/IFNGR2, and these polymorphisms seem to influence susceptibility to several infectious diseases, including tuberculosis." (PMID 26000298, 2015). "However, the association between IFNGR1 and LTBI/tuberculosis has not been studied." (PMID 31687049, 2019).
autoimmune disease (11 papers, 2006 to 2025). A disorder resulting from loss of function or tissue destruction of an organ or multiple organs, arising from humoral or cellular immune responses of the individual to their own tissue constituents. "In summary, this study demonstrates that SNPs carried on the ∼109 kb SLE risk haplotype facilitate hypermorphic IL20RA and IFNGR1 expression, while suppressing TNFAIP3 expression, adding to the mechanistic potency of this critically important locus in autoimmune disease pathology." (PMID 36199584, 2022). "IFNGR1, along with type I IFN receptors, which were also upregulated in our study, may be of particular interest in IC/BPS since they are considered to be pivotal players in various inflammatory and autoimmune diseases." (PMID 36045687, 2022).
malaria (9 papers, 2012 to 2024). Malaria is a serious and sometimes fatal disease caused by a parasite that commonly infects a certain type of mosquito which feeds on humans. "Befitting any general immune response mechanism, various cytokines may potentially modulate ICAM1 expression, of which we have found evidence for statistical association of IL1, IL4 (and its receptor, IL4R), IL6, IL13, TLR2, TLR4, and IFNG (and its receptor, IFNGR1) polymorphisms with malaria." (PMID 37287037, 2023). "The results herein provide evidence for the association of TLR4 and related genes, ICAM1, IFNGR1, IL13, and IL6, as well as ABO, with the incidence of clinical malaria." (PMID 37287037, 2023). "This study explored the role of IFNGR1 in the pathogenesis of placental pathology using a mouse model of malaria during pregnancy." (PMID 29117241, 2017). "In the present study, we explored the role of IFN-γ receptor 1 (IFNGR1) signaling in placental pathology during severe malaria using luciferase-expressing rodent malaria parasites, P. berghei NK65 (PbNK65L)." (PMID 29117241, 2017). "The upregulation of these chemokines was critically dependent on IFN-γ signaling as demonstrated by their virtual absence in Ifngr1-null animals during acute malaria." (PMID 23762028, 2013). "Based on these preclinical findings, additional investigations are required to establish whether maternal IFNGR1 signaling is also involved in developing placental pathology in clinical cases of severe malaria." (PMID 29117241, 2017). "Previous studies show that TFAP2A (AP2) regulates the transcription of IFN-γ Receptor 1 (IFNGR1), and that elevated IFN-γ production is protective against infection with malaria." (PMID 37704951, 2023). "Upon treatment with plasma from malaria patients, HEK293T cells with intact IFNγR1 expression displayed lower ONNV infection compared with untreated controls." (PMID 35039441, 2022). "Our finding that IFNGR1 signaling plays a central role in the development of placental pathology during malaria in pregnancy suggests that blocking IFNGR1 signaling may be effective for the prevention of adverse pregnancy outcomes during infection with malaria parasites." (PMID 29117241, 2017). "Hence, there remains the possibility that the lack of progenitor mobilization in Ifngr1- and Ccr2-null animals during acute malaria is not fully reflecting the situation in wild type hosts, a crucial question for future studies." (PMID 23762028, 2013).
immune deficiency (6 papers, 2016 to 2026). "IFNGR1 deficiency is associated with immunodeficiency 27A and 27B, increasing the risk of mycobacterial infections and infections by intracellular microorganisms, viruses, Toxoplasma, and Histoplasma." (PMID 40062101, 2025). "IFNGR1 deficiency is associated with immunodeficiency 27 A and 27B, which leads to an increased risk of mycobacterial infections." (PMID 40062101, 2025). "It is hypothesized that IFNGR1 gene mutation affects the binding and production of interferon-γ, causing immune deficiency or impaired immunity, thus increasing the risk of TM infection." (PMID 37926601, 2024). "Furthermore, IFNGR1 deficiency is a rare immune deficiency characterized by selective susceptibility to mycobacterial disease due to IFNGR1 gene mutations." (PMID 33802085, 2021). "Mutations in 6 genes (IL12RB1, CYBB, IFNGR1, IL2RG, STAT1, and RAG1) account for 66% of BCG-associated immunodeficiency mutations." (PMID 41748971, 2026).
lung carcinoma (6 papers, 2021 to 2025). "IFNGR1 and IFNGR2, the cognate receptors of IFNG, were expressed in both monocytes in blood and macrophages in lung cancer." (PMID 35069521, 2021). "Furthermore, impairment of IFN-γ signaling by knocking down IFNGR1, led to resistance to HER2-TCB in cell lines from HER2-positive ovarian and lung cancers." (PMID 33623012, 2021).
ovarian carcinoma (6 papers, 2014 to 2023). A malignant neoplasm originating from the surface ovarian epithelium. "Reduced expression of IFNGR1 has been reported to be associated with clinicopathologic characteristics of esophageal cancer and prognosis of ovarian cancer." (PMID 25350395, 2014). "On the contrary, mouse ovarian cancer HM1 cell-induced tumors with Ifngr1 knockdown grew more slowly than control tumors." (PMID 32155707, 2020). "The expression level of IFNGR1 in a typical ovarian cancer population varies, with 22% of them displaying a complete loss of the IFNγ receptor." (PMID 25079112, 2014). "Among top 20 ranked miRNA-mRNA interaction pairs, the roles of four targets including PLAGL1, MTUS1, MEF and IFNGR1 have been reported in ovarian cancer." (PMID 25079112, 2014). "Therefore, low expression of IFNGR1 could be regarded as an independent prognostic marker in ovarian cancer." (PMID 25079112, 2014).
glioblastoma (5 papers, 2019 to 2023). The most malignant astrocytic tumor (WHO grade IV). "Given that the loss of IFNγR1 signaling has been implicated as major mechanism of glioblastoma-intrinsic resistance to CAR T cells, successful immunotherapy requires maintenance of the physical mechanics of cytotoxicity and an adequate synapse between tumor and CAR T cells." (PMID 38132354, 2023). "To determine whether our findings were specific to leukemia cells, we examined the effect of tumor-intrinsic Ifngr1 deficiency on response to CAR-T cells in a murine model of glioblastoma, GL261." (PMID 38052854, 2023). "g., IFNGR1, JAK1, and JAK2) made glioblastoma cells more resistant to CAR T cells both in vitro and in vivo." (PMID 36389701, 2022).
parasitemia (5 papers, 2012 to 2021). "The course of parasitemia in IFNGR1-KO postpartum mice infected with Pb ANKA was similar to the course in infected wild-type postpartum mice." (PMID 34644348, 2021). "Consistent with previous reports, naive Ifngr1-/- mice developed high parasitemia that recrudesced multiple times but was controlled to sub-patent levels by 40–50 days post-infection." (PMID 27583554, 2016). "Parasitemia in pregnant and nonpregnant mice infected with PbNK65L was not affected by deficiency of IFNGR1." (PMID 29117241, 2017). "We and others have previously shown that mice lacking a subunit of the interferon gamma (IFN-γ) receptor (Ifngr1-/-) experience higher parasitemias than wild-type mice, but eventually clear infection." (PMID 27583554, 2016).
pulmonary tuberculosis (5 papers, 2015 to 2022). A bacterial infection that affects the lungs and is caused by Mycobacterium tuberculosis. "Genetic variation in IFNGR1 is associated with susceptibility to pulmonary tuberculosis, Helicobacter pylori and early gastric carcinoma." (PMID 35837092, 2022). "In the current study we aimed to explore the genetic association of polymorphisms of IFNG and IFNGR1 with the risk of pulmonary tuberculosis (PTB) in the Chinese Tibetan population." (PMID 29228700, 2017). "In this study, we aim to investigate the association of IFNG/IFNGR1 polymorphisms with healthy control subjects (HCS), latent tuberculosis infection (LTBI), and pulmonary TB (PTB)." (PMID 31687049, 2019). "Patients with untreated pulmonary tuberculosis were reported to have decreased IFNGR1 expression on circulating CD14+ monocytes compared to healthy uninfected controls." (PMID 28542482, 2017). "Previous studies indicated that single-nucleotide polymorphisms (SNPs) of interferon gamma (IFNG) and IFNG receptor 1 (IFNGR1) may be involved in the pathogenesis of pulmonary tuberculosis (PTB) in different populations." (PMID 31687049, 2019).
gastric carcinoma (4 papers, 2014 to 2022). A carcinoma that arises from epithelial cells of the stomach. "Published studies have reported that polymorphisms in IFNGR1 are significantly associated with susceptibility of chronic hepatitis B virus infection, early gastric carcinoma, and rectal cancer." (PMID 25350395, 2014). "Canedo et al9 found that IFNGR1 −56C/T gene polymorphism is associated with an increased risk of early gastric carcinoma, but there have not been any reports on the aberrant expression of IFNGR1 in gastric cancer." (PMID 30873760, 2019). "However, in this study, we found the levels of IFNGR1 were obviously increased in gastric cancer." (PMID 30873760, 2019).
glioma (4 papers, 2022 to 2023). A benign or malignant brain and spinal cord tumor that arises from glial cells (astrocytes, oligodendrocytes, ependymal cells). "In this study, we have developed a concise IFNG-related gene signature to characterize the prognosis of gliomas based on the expression of IFNGR1 and IFNGR2." (PMID 35492352, 2022). "IFNGR1 and IFNGR2 were used as concise IFNG-related gene signature based on which the IFNGR score well-characterized the IFNG response in the glioma microenvironment." (PMID 35492352, 2022). "A recent study indicated that the binding of T cells to glioma cells calls for the IFNγR signaling pathway (IFNGR1, JAK1 and JAK2) in which IFNGR1 was found necessary for this kind of cell-cell adhesion." (PMID 36309750, 2022). "In addition, GO analysis corroborates the pro-inflammatory microenvironment of the IFNGR score-high group, suggesting that the upregulation of IFNGR1 and IFNGR2 was associated with enhanced inflammatory and immune response in gliomas." (PMID 35492352, 2022). "This suggests an increased interaction between T cells and glioma cells and that high neoplastic cells might escape this interaction by downregulating IFNGR1 to decrease T cell binding." (PMID 36309750, 2022). "Although various IFNG-related inflammatory responses may be active in the glioma microenvironment with elevated IFNGR scores, macrophages with increased expression of IFNGR1 and IFNGR2 were preferentially subject to transcriptional regulation by NF-κB and STAT3." (PMID 35492352, 2022). "Nevertheless, some genes, such as BAX, IFNGR1, and PDIA3, showed a decrease in their copy number and exhibited elevated expression levels in glioma." (PMID 36428756, 2022). "Additionally, cell communication analysis confirmed that the high NAS group showed more inter-cell communication between immune cells and inflammation-related glioma cells and that high neoplastic glioma cells might escape T cell binding by downregulating IFNGR1." (PMID 36309750, 2022). "Notably, IFNGR1 and IFNGR2 were preferentially expressed by the Mono/Macro cells in the glioma microenvironment and were significantly correlated with M2 macrophage." (PMID 35492352, 2022). "To our knowledge, we have for the first time explored the role of IFNGR1 and IFNGR2 in gliomas." (PMID 35492352, 2022). "Therefore, IFNGR1 and IFNGR2 may also constitute a genetic metric of clinical implications in glioma." (PMID 35492352, 2022). "Results showed that expressions of IFNGR1 and JAK1 were significantly higher compared to the other three glioma cell types, but expression of JAK2 was not obviously different." (PMID 36309750, 2022).
leukemia (4 papers, 2021 to 2024). A malignant (clonal) hematologic disorder, involving hematopoietic stem cells and characterized by the presence of primitive or atypical myeloid or lymphoid cells in the bone marrow and the blood. "Given that IFN-γ produced by leukemia cells may function directly on the host immune system to mediate immune evasion, we first investigated the expression pattern of its receptor IFNGR1 in different cell types." (PMID 34906138, 2021). "This phenotype is accompanied by induction of IFN-γ production in the leukemia cells and transplantation of control SCLL cells into IFNGR1 null mice shows impaired MDSC induction and mitigated leukemogenesis." (PMID 34906138, 2021). "In vitro and in vivo expression assays and engraftment with interferon gamma receptor-1 (IFNGR1) null mice and IFNG KO SCLL cells, showed the leukemia cells produced IFN-γ directly participating in the induction of MDSCs to establish immune evasion." (PMID 34906138, 2021).
lupus (4 papers, 2021 to 2023). "Elevated expression of IFNGR1 and subsequent IFNγ signaling activation promotes the loss of self-tolerance and production of autoantibodies in murine lupus models." (PMID 36199584, 2022). "Previous studies have demonstrated that genetic polymorphisms of IFNG and IFNGR1 were correlated with tuberculosis infection, systemic lupus erythematosus, etc.." (PMID 34646402, 2021).
primary immunodeficiency (4 papers, 2016 to 2021). "Subsequently, an underlying primary immunodeficiency associated with a novel nonsense homozygous mutation in the IFNGR1 gene was characterized." (PMID 27868075, 2016). "Though T cell immunity is clearly important for anti-mycobacterial defense, myeloid cells are also essential, as demonstrated by many forms of primary immunodeficiency such as GATA2 haploinsufficiency, IFNGR1/2 deficiency, Chronic granulomatous disease, and IRF8 deficiency." (PMID 30984189, 2019).